PRDX2 (peroxiredoxin 2)
Diseases named in the same sentence as PRDX2 in open-access papers (continued):
Sharing a sentence is not in itself a finding about the gene and the disease.
oral squamous cell carcinoma (5 papers, 2020 to 2025). "HOXA10 promotes the expression of PRDX2 and inhibits ferroptosis in oral squamous cell carcinoma (OSCC)." (PMID 40498062, 2025). "Peroxiredoxin 2 (PRDX2) is upregulated in various cancers including oral squamous cell carcinoma (OSCC)." (PMID 33332365, 2020). "Oral squamous cell carcinoma was indicated to have overexpression of PRDX1, PRDX2, and PRDX6." (PMID 40281661, 2025). "In addition, PRDX1, PRDX2, and PRDX6 have also been reported to be overexpressed in oral squamous cell carcinoma." (PMID 36969053, 2023). "Though PRDX2 did not predict HNSCC prognosis, we still found that PRDX2 was positively associated with aggressive phenotype, such as angiogenesis, EMT, invasion, metastasis and proliferation, which was in line with oral squamous cell carcinoma (OSCC)." (PMID 35350568, 2022). "However, the function of PRDX2 in oral carcinogenesis remains unclear and the mechanism leading to upregulation of PRDX2 in cancer, particularly in oral squamous cell carcinoma (OSCC), has not been explored." (PMID 33332365, 2020).
acute myocardial infarction (4 papers, 2017 to 2024). Necrosis of the myocardium, as a result of interruption of the blood supply to the area. "It was found in the study of myocardial infarction model that the overexpression of PRDX2 could induce a decreased production of ROS, alleviating the myocardial injury caused by myocardial infarction." (PMID 35378825, 2022). "In this study, we investigate the diverse influence of PRDX2 on TLR4 and VEGF in myocyte hypertrophy and acute myocardial infarction (AMI) from data acquired through clinical trials, H9c2 cells and in a mouse model system." (PMID 28765537, 2017). "But the role of PRDX2 in acute myocardial infarction (AMI) is not clear." (PMID 28765537, 2017).
atherosclerosis (4 papers, 2021 to 2024). A disease characterized by the build-up of fatty material and calcium deposition in the arterial wall resulting in partial or complete occlusion of the arterial lumen. "Additionally, PRDX2 protein levels were up-regulated in human carotid artery tissues with atherosclerosis compared to normal carotid artery tissues, suggesting that PRDX2 up-regulation may be a stress response." (PMID 39338362, 2024). "For example, PRDX2 can inhibit H2O2 production induced by cytokines in ECs ex vivo and slow atherosclerosis in animal models of disease." (PMID 38958135, 2024). "Peroxiredoxin 2 (PRDX2), an inhibitor of reactive oxygen species (ROS), is potentially involved in the progression of atherosclerosis (AS)." (PMID 33791345, 2021).
diabetes (4 papers, 2022 to 2025). "A recent study showed that Prdx2 overexpression attenuated cardiac microvascular injury in diabetes by inhibiting mitochondria‐associated ferroptosis." (PMID 39763059, 2025). "Previous studies suggest that PRDX2 overexpression can prevent pancreatic cell apoptosis induced by oxidative stress and reduce the risk of developing diabetes." (PMID 36141135, 2022). "PRDX2 overexpression can prevent pancreatic β cell apoptosis induced by oxidative stress and reduce the risk of developing diabetes." (PMID 36141135, 2022). "As reported in55, there are beneficial effects of cardiac microvascular protection in diabetes mellitus through PRDX2 pathways." (PMID 37365269, 2023).
Insulin resistance (4 papers, 2018 to 2023). Increased resistance towards insulin, that is, diminished effectiveness of insulin in reducing blood glucose levels. "GAPDH monomer combined with body mass index (BMI) and PRDX2 S-S dimer combined with homeostatic model assessment for insulin resistance (HOMA-IR) showed to be very promising biomarkers to predict OSA and OSA severity, respectively." (PMID 33256145, 2020). "The PRDX2 dimer/monomer ratio was unchanged in all insulin resistance models, indicating that cytosolic peroxide levels were unchanged." (PMID 29599292, 2018). "Considering the paradoxical regulation of PRDX2, a protective gene in obesity, we analyzed the proportion of LM2 and discovered it to be decreased in patients with obesity, independently of insulin resistance, compared with lean individuals." (PMID 37414931, 2023). "We next established the dose of MitoPQ that specifically induced PRDX3 dimerization without affecting cytosolic PRDX2 in 3T3-L1 adipocytes treated with MitoPQ for 2 h to mimic the subcellular oxidative burden in insulin resistance." (PMID 29599292, 2018).
liver fibrosis (4 papers, 2010 to 2025). "Collagen proportionate area (CPA), hydroxyproline quantification, and assessment of fibrogenic gene expression (Acta2, Col1a, Tgfb1, and Timp1) showed a minor effect of Prdx2 KO on liver fibrosis." (PMID 40932790, 2025). "We then assessed the effect of Prdx2 KO on liver fibrosis and steatosis." (PMID 40932790, 2025). "Peroxiredoxin 2 is upregulated in fibrotic patients and could be potentially used in early diagnosis of HBV related liver fibrosis." (PMID 23259639, 2012).
lung adenocarcinoma (4 papers, 2019 to 2025). A carcinoma that arises from the lung and is characterized by the presence of malignant glandular epithelial cells. "In lung adenocarcinoma, PRDX2 levels correlate with both overall survival (OS) and disease-free survival (DFS)." (PMID 40645965, 2025). "The results showed that Prdx2 and Prdx4 were expressed higher in large cell lung carcinoma, lung adenocarcinoma, and squamous cell lung carcinoma compared with that in normal lung tissues." (PMID 30988280, 2019).
pancreatic cancer (4 papers, 2017 to 2023). "In pancreatic cancer, a proteomic study using gemcitabine-sensitive KLM1 and -resistant KLM1-R cells showed that PRDX2 was significantly up-regulated in KLM1-R cells." (PMID 28432271, 2017).
acute myeloid leukemia (3 papers, 2017 to 2021). Acute myeloid leukemia (AML) is a group of neoplasms arising from precursor cells committed to the myeloid cell-line differentiation. "Similarly, there was also a significant reduction of the expression of PRDX2 in acute myeloid leukemia (AML)." (PMID 32908916, 2020). "PRDX2, the peroxidase activity of which is activated by CDK2, inhibits the differentiation of acute myeloid leukemia (AML) cells." (PMID 33771165, 2021). "Similarly, PRDX2 is epigenetically silenced and inhibits c-Myc-induced leukemogenesis in acute myeloid leukemia (AML)." (PMID 29258530, 2017).
anemia (3 papers, 2021 to 2025). A reduction in the number of red blood cells, the amount of hemoglobin, and/or the volume of packed red blood cells. "Altered PRDX2 expression has been associated with hematological conditions such as anemia, which frequently presents with anisocytosis." (PMID 40128671, 2025). "Although previous studies have shown that Prdx2 homozygous null mice have anemia and enlarged spleens, due to the major antioxidant role of PRDX2 in erythrocytes, no liver or kidney toxicity was reported." (PMID 40932790, 2025). "Increased bone marrow erythropoiesis secondary to anemia leads to upregulation of PRDX2, which is released in the exosomes and acts to induce osteoclast formation." (PMID 33587325, 2021). "Thus, increased bone marrow erythropoiesis secondary to anemia leads to upregulation of PRDX2, which is released in the exosomes and acts to induce osteoclast formation." (PMID 33587325, 2021).
hereditary spherocytosis (3 papers, 2020 to 2024). Hereditary spherocytosis is a congenital hemolytic anemia with a wide clinical spectrum (from symptom-free carriers to severe hemolysis) characterized by anemia, variable jaundice, splenomegaly and cholelithiasis. "It is thought that PRDX2 associates with the membrane via binding to band 3, and its membrane association is increased in cases of hereditary spherocytosis in response to oxidative stress." (PMID 32411010, 2020).
Hypertension (3 papers, 2024 to 2025). The presence of chronic increased pressure in the systemic arterial system. "This supports the evidence that PRDX2 is involved in the regulation of myocardial hypertrophy and cardiomyocyte apoptosis in hypertension." (PMID 39338362, 2024).
kidney cancer (3 papers, 2021 to 2025). Primary or metastatic malignant neoplasm involving the kidney. "The PRDX2 gene has been found to be upregulated in several cancers, and most recently, PRDX2 has been included in a 6-gene anti-oxidant signature that effectively predicts the prognosis of patients with kidney cancer." (PMID 35771847, 2022). "Increased or decreased levels of PRDXs mRNA expression levels were found among 33 tumor types, such as PRDX1, PRDX2, PRDX4 and PRDX5 increased in several cancer types, while PRDX3 and PRDX6 decreased in there types of kidney cancer (KIRP, KIRC and KICH)." (PMID 34246267, 2021). "Notably, when compared to adjacent or normal tissues, PRDX1, PRDX2, PRDX4 and PRDX5 were significantly up-regulated expression in several cancer types (UCEC, READ, BLCA, BRCA, CHOL, COAD, LIHC, THCA), while PRDX3 and PRDX6 were down-regulated expression in kidney cancers." (PMID 34246267, 2021).
lymphoma (3 papers, 2016 to 2020). A malignant (clonal) proliferation of B- lymphocytes or T- lymphocytes which involves the lymph nodes, bone marrow and/or extranodal sites. "Concomitant knockdown of PRDX1 and PRDX2 significantly attenuated the growth rate of lymphoma cells." (PMID 26636537, 2016). "Particularly, we show that PRDX1 and PRDX2 are abundantly expressed in B cell-derived primary lymphoma cells and cell lines as well as that they promote lymphoma cell proliferation and survival." (PMID 26636537, 2016). "PRDX2 has also been shown to induce the growth of lymphoma cells." (PMID 32666718, 2020). "Furthermore, in a model of BL cell lines, we show that concomitant downregulation of PRDX1 and PRDX2 diminishes the growth rate of lymphoma cells." (PMID 26636537, 2016). "Additionally, it has been reported that there is a direct physical interaction between collapsing response mediator protein 2 (CRMP2) which regulates microtubule structure during migration or neuronal development and cytoplasmic Prdx2 in Jurkat T-lymphoma cells." (PMID 33182509, 2020). "Considering that TRX1 is already a known therapeutic target in lymphoma, we focused on two PRDX cytoplasmic isoforms, PRDX1 and PRDX2." (PMID 26636537, 2016).
Obesity (3 papers, 2021 to 2025). Accumulation of substantial excess body fat. "Together, the depletion of APOD and PRDX2 highlights a broader impairment in the antioxidative and anti-inflammatory functions of adiposome cargo in obesity." (PMID 40981199, 2025). "Interestingly, PRDX2 was upregulated in both insulin-sensitive and insulin-resistant patients, suggesting obesity as a major driver of PRDX2 upregulation." (PMID 37414931, 2023). "This suggests that most secreted PRDX2 in obesity originates from LM2 cells." (PMID 37414931, 2023). "Collectively, the reciprocal shift from protective proteins like TTR, APOD, and PRDX2 to pro-inflammatory mediators such as CRP and C9 highlights a coordinated reprogramming of adiposome cargo in obesity." (PMID 40981199, 2025). "In Gal-9−/− C57BL/6J mice, they were resistant to diet-induced obesity and the absence of Gal-9 ameliorated the oxidative stress by shifting lower dimer/monomer ratio of PRDX2 in 3T3L1 adipocytes." (PMID 33727589, 2021).
psoriasis (3 papers, 2013 to 2025). An autoimmune condition characterized by red, well-delineated plaques with silvery scales that are usually on the extensor surfaces and scalp. "Accumulating evidence suggests that PRDX2 overexpression is implicated in tumorigenesis and the progression of various inflammatory diseases, including psoriasis, inflammatory bowel disease, and RA." (PMID 40443720, 2025). "The upregulation of PRDX2, another important antioxidative enzyme, has also been found in psoriasis." (PMID 26966508, 2016). "It is worth noting that upregulation of PRDX2 has also been found in psoriasis, a hyperproliferative skin disease characterized by abnormal keratinocyte proliferation." (PMID 23852020, 2013).
renal fibrosis (3 papers, 2016 to 2023). A final common manifestation of a wide variety of chronic kidney diseases characterized by glomerulosclerosis and tubulointerstitial fibrosis. "To determine involvement of Prdxs in renal fibrosis, we analyzed the expression pattern of Prdxs isotypes (Prdx1, Prdx2, Prdx3, Prdx4, Prdx5, and Prdx6) in the cortex/outer stripe of outer medulla of UUO kidney." (PMID 26872211, 2016). "As in the case of Prdx2-mediated Stat3 regulation, further studies are needed to determine whether PrdxV modulates renal fibrosis by peroxidase-mediated redox signaling in regulating TGF-B-induced Stat3 activation." (PMID 31217524, 2019). "Finally, PRDX2 which encodes a member of the peroxiredoxin family of antioxidant enzymes, was found up-regulated among 30 proteins in fibrotic kidney fibroblasts (TK188) compared to normal kidney fibroblast (TK173), suggesting a role in the progression of renal fibrosis." (PMID 38322285, 2023).
Stroke (3 papers, 2014 to 2025). Sudden impairment of blood flow to a part of the brain due to occlusion or rupture of an artery to the brain. "Peroxiredoxin-2 (PRDX2) is the third most abundant protein in red blood cells and acts as an injury factor in brain injury after stroke." (PMID 36187347, 2022). "Moreover, the PRDX2 expression 24 h post-stroke was enhanced compared to the 6 h, 3 d and 7 d groups (p < 0.0001, p < 0.05 and p < 0.001, respectively)." (PMID 40332314, 2025). "In our study, we observed an increased PRDX2 and PRDX5 gene expression in the hemisphere affected by stroke 24 h post-induction (p < 0.0001 and p < 0.01, respectively)." (PMID 40332314, 2025). "PRDX2 and PRDX6 have been shown to have a positive effect on brain tissue after stroke by reducing the level of ROS and thus its harmful effects and mitigating neuronal apoptosis in rats and dogs." (PMID 40332314, 2025). "miR-122 regulates the expression of peroxiredoxin 2, a DAMP involved in immune activation post stroke." (PMID 24911610, 2014). "Hypoxic conditions, thrombin, PRDX2, and iron contribute to the increase of LCN2 after stroke." (PMID 36187347, 2022).
subarachnoid hemorrhage (3 papers, 2018 to 2023). A serious neurological disorder characterized by intracranial hemorrhage into the subarachnoid space. "Extracellular Prdx2 in the cerebrospinal fluid of subarachnoid hemorrhage patients can interact with microglial toll-like 4 receptors (TLR4), inducing apoptosis of neurons." (PMID 37237878, 2023). "Expression of Prdx2 was found to be elevated after subarachnoid hemorrhage and to protect again brain injury." (PMID 37237878, 2023). "However, Prdx2 was the second most abundant protein in the cerebrospinal fluid of subarachnoid hemorrhage and traumatic brain injury patients due to release from necrotic neurons." (PMID 37237878, 2023). "It was proposed that the levels of Prdx2 in the CSF and the ratio of Prdx2 in the cerebrospinal fluid and the blood within 3 days of onset can be used as a biomarker to detect the severity of the disease and the clinical status of subarachnoid hemorrhage patients." (PMID 37237878, 2023).
viral infection (3 papers, 2014 to 2021). "In addition to providing antioxidant protection, PRDX2 may also bolster CD8+ T-cells against viral infection." (PMID 33656056, 2021). "Release of TXN1 was also markedly induced by viral infection while, unlike PRDX1 and PRDX2, little or no TXN1 was released in non-infected cells." (PMID 25985305, 2015).
abdominal aortic aneurysm (2 papers, 2020 to 2025). Enlargement and ballooning of the vessel that supplies arterial blood to the abdomen, pelvis and legs. "Another study confirmed that Prdx2 deficiency increases oxidative stress and inflammatory responses and accelerates angiotensin II‐induced abdominal aortic aneurysm." (PMID 39763059, 2025).
abortion (2 papers, 2019 to 2021). the ending of pregnancy by removing a fetus or embryo before it can survive outside the uterus. "Moreover, injection of an anti-PRDX2 neutralizing antibody increases NK-cell cytotoxicity and raises the fetal absorption rate in an abortion-prone mouse model." (PMID 33763465, 2021). "Meanwhile, using PRM, we identified three proteins that were closely related to abortion, B4DTF1 (highly similar to PSG1), P11464 (PSG1), and B4DF70 (highly similar to Prdx-2)." (PMID 31636515, 2019).
anaplastic thyroid cancer (2 papers, 2015 to 2022). "PRDX1, PRDX2, and PRDX3 expressions downregulated in papillary and anaplastic thyroid cancers, PRDX4 mRNA expression was moderately increased in anaplastic thyroid cancer tissues, and PRDX6 expression status showed similar levels as well as normal thyroid and thyroid cancers." (PMID 35571253, 2022). "PRDX1, PRDX2, and PRDX3 mRNA synthesis decreased in papillary and anaplastic thyroid cancers, PRDX4 mRNA expression was moderately increased in anaplastic thyroid cancer tissues, and PRDX6 expression status was at similar levels in normal thyroid and thyroid cancers." (PMID 26664298, 2015).
asthma (2 papers, 2021 to 2022). "Increased sensitivity of Treg cells from adults with asthma to H2O2 resulted from a reduction of peroxiredoxin-2, -3, and -4 and increased pERK1/2 via impaired Ca2+ response in these cells." (PMID 34072455, 2021). "Increased sensitivity of Treg cells from adults with asthma to H2O2 resulted from a reduction of peroxiredoxin-2, -3, -4 and increased pERK1/2 via impaired Ca2+ response in these cells." (PMID 34072455, 2021). "Reduced PRDX2 protein expression has been also established in asthma patients." (PMID 35628331, 2022). "In agreement with the results of microarray analysis of Tet-On® Jurkat cells, mRNA expression of peroxiredoxin (PRDX)-2, -3, and -4 in Treg cells from adults with asthma was decreased compared with Treg cells from adults without asthma." (PMID 34072455, 2021).
beta thalassemia (2 papers, 2018 to 2022). Beta-thalassemia (BT) is characterized by deficiency (Beta+) or absence (Beta0) of synthesis of the beta globin chains of hemoglobin (Hb). "At the same time, RBCs in beta-thalassemia trait seem to possess an advantageous genetic regulation of antioxidant enzymes, leading to upregulated expression of peroxiredoxin-2 and superoxide dismutase." (PMID 35755442, 2022).
Burkitt lymphoma (2 papers, 2018 to 2023). A rare form of malignant mature B-cell non-Hodgkin lymphoma. "Interestingly, the naturally occurring small-molecular peptidomimetic SK053 targeted PRDX1 and PRDX2, leading to cell cycle arrest and apoptosis in Burkitt lymphoma cells." (PMID 36839749, 2023).
diabetic kidney disease (2 papers, 2022). Progressive kidney disorder caused by vascular damage to the glomerular capillaries, in patients with diabetes mellitus. "The changes in oxidative stress in diabetic kidney disease and other pathological processes are related to the expression of PRDX2 and related pathways." (PMID 36141135, 2022).
endometriosis (2 papers, 2018 to 2020). The growth of functional endometrial tissue in anatomic sites outside the uterine body. "Repeated genes associated with P-phase (ACTB, ANXA4, BPIFB1, EPHX1, MUC5B, PRDX2, and VIM) could indicate stronger genetic causes associated with pathophysiology of endometriosis." (PMID 32474803, 2020).